ADAM12 (ADAM metallopeptidase domain 12)
Diseases named in the same sentence as ADAM12 in open-access papers (continued):
Sharing a sentence is not in itself a finding about the gene and the disease.
cancer (continued). "Subsequent in vitro expression showed that some of these mutants are more prone to ADAM12-mediated shedding and that the shed ectodomain can enhance gelatin degradation by cancer cells." (PMID 31013576, 2019). "Several ADAM family members, particularly ADAM9, ADAM10, ADAM12, ADAM15 and ADAM17, have been implicated in cancer formation and progression." (PMID 30081852, 2018). "In normal brain tissues, ADAR2 edits nearly 100% of miR589-3p to target and reduce expression of disintegrin and metalloproteinase domain-containing protein 12 (ADAM12), a metalloprotease that promotes cancer metastasis." (PMID 30619092, 2018). "As the EGFR signaling pathway is frequently activated in TNBC, ADAM12-mediated increase of EGFR activity should be the most relevant in this type of cancer." (PMID 28148288, 2017). "To examine the generalizability of these results, we also used siRNA to silence ADAM12 in a panel of cancer cell lines." (PMID 26477568, 2015). "ADAM12 is an active proteinase, which is highly expressed in remodelling and fast-growing tissues such as the placenta and malignant tumours." (PMID 25667922, 2015). "Up-regulation of ADAM12 has been described in numerous cancers, including breast, colon, hepatocellular carcinomas, glioblastomas, stomach, oral cavity, bladder, lung and giant cell tumors of bone." (PMID 26407179, 2015). "Next, we analyzed ADAM12-La and ADAM12-Lb expression in three cancer cell lines, Hs578T, MDA-MB-231, and MCF10DCIS.com." (PMID 24116070, 2013). "To further confirm the identity of the ADAM12-La and ADAM12-Lb proteins detected in cancer cells, we generated siRNAs selectively targeting each variant." (PMID 24116070, 2013). "Recently, ADAM12 has been shown to be involved in the formation of invadopodia, cellular structures that aid cancer cell invasion, in head and neck, lung, and pancreatic cancer cells." (PMID 24116070, 2013). "ADAM12 as well as several members of the ADAM family are over-expressed in various cancers, correlating with disease stage." (PMID 22662180, 2012). "We demonstrate in the present paper that cultured BZR lung-derived cancer cell lines expressed ADAM-12 mRNA, while 16-HBE and BEAS-2B cells derived from normal epithelial cells did not express significant levels of ADAM-12 mRNA." (PMID 16495931, 2006). "Also, the expression of PDGF‐bb, which is a promoter of cancer cell proliferation, was significantly reduced by suppression of ADAM12 and CYP1B1 in obese‐derived adipocytes." (PMID 39806854, 2025). "The findings reported here add new insight into the underlying molecular mechanisms, indicating that sBSG, proteolytically shed by ADAM12 from the cancer cell surface, binds β1 integrin at the same or neighboring cells to induce MMP activation and β1 integrin-dependent cancer cell migration." (PMID 38892056, 2024). "In summary, we showed that neither loss nor gain of ADAM12 expression had any effects on the survival to radiation of the tested cancer cell lines in vitro." (PMID 37495855, 2023). "In relation to cancer, this substrate plays a role in determining how invasive the cancer cells may be, and in relation to Alzheimer’s disease, alongside the gene ADAM12, it moderates the neurotoxicity of β-amyloid." (PMID 37270590, 2023). "Furthermore, we assessed ADAM12 expression in 30 pairs of ccRCC and adjacent normal kidney tissues and discovered that it was significantly upregulated in cancer tissues." (PMID 36717944, 2023). "ADAM12 is involved in multiple pathological processes and is most extensively known to be upregulated in cancer, where it may be of significant prognostic value." (PMID 35413826, 2022). "In particular, CDK6 was chosen for the function “pathway in cancer”, ADAM12 for the function “signaling by EGFR”, HDAC4 was selected for the function “regulation of cell differentiation”, and finally Bcl2 for the function “negative regulation of apoptotic processing”." (PMID 36498866, 2022).
cancer (continued). "In addition, the expression profile of ADAM12 and its potential prognostic value and therapeutic targets in different cancers, including thyroid cancer, lung adenocarcinoma, and pancreatic adenocarcinoma, have been reported." (PMID 34604068, 2021). "We thus conclude that the ADAM12, MMP1, SERPINE1, PLOD3, and P4HA3 signature showed a close association with a pan‐cancer effect on prognosis and is related to ECM proteins in the TME which corresponding with immunologically “cold” cancer types." (PMID 34121340, 2021). "In addition, ADAM12 regulates a variety of cellular processes in cancers via multiple signaling transduction pathways, including Akt." (PMID 33923541, 2021). "UALCAN was used to further analyze ADAM12 expression in human cancers." (PMID 34604068, 2021). "Therefore, our results clearly reveal that ADAM12 is involved in many aspects of cancer development." (PMID 34604068, 2021). "In addition, VEGFα, MMP2, ADAM12 and Vim, which are produced by cancer cells, have been reported to disrupt vascular integrity." (PMID 32537867, 2020). "As ADAM12 is a Src substrate and ADAM12 phosphorylation aids membrane targeting, it is possible that Src and/or Tks5 facilitate recruitment of ADAM12 in the formation of mature and active invadopodia structures in cancer cells." (PMID 31999741, 2020). "This provides a mechanism for the known responsiveness of ADAM12 to TGF-β in cancer cells." (PMID 30753595, 2019). "Moreover, CRISPR/Cas9-mediated knockout of ADAM12 in human HeLa carcinoma cells results in reduced shedding of the basigin reporter, which can be rescued by ADAM12 re-expression." (PMID 31013576, 2019). "Furthermore, ADAM12 has been shown to participate in matrix remodeling by cleavage of extracellular matrix proteins, suggesting involvement in cancer invasion and metastasis formation." (PMID 30442938, 2018). "In the NKI database, ADAM12 mRNA levels (transcript variant 1) were more frequently upregulated in claudin-low (CL) tumors compared to basal (B), luminal A/B (LumA/B), HER2-enriched (HER2+), or normal-like (NL) cancers." (PMID 28148288, 2017). "ADAM12 inhibitory antibodies or genetically altered tissue inhibitor of metalloproteinases 2 (TIMP2) for specifically blocking ADAM12 or recombinant ADAM12 prodomain still need to be investigated in animal models of cancer cell migration." (PMID 28260841, 2017). "Over-expression of ADAM12 was also observed in several human carcinomas." (PMID 27270327, 2016). "In addition genome-wide analyses of human breast and colorectal cancers identified ADAM12 as a new candidate cancer gene." (PMID 26407179, 2015). "Furthermore, ADAM12 expression is strongly elevated in many cancers, including breast, head and neck, bone, lung, bladder, prostate, and brain cancers, as well as aggressive fibromatosis." (PMID 24116070, 2013). "ADAM12 promotes tumor progression in transgenic mouse models of breast and prostate cancer and several ADAMs are considered as promising targets for cancer therapy." (PMID 22662180, 2012). "Interestingly, many of the DMGs identified had multiple roles and several were potential cancer biomarkers or were previously shown to be implicated in various types of cancers, including ABLIM1, ADAM12, ARHGEF4, FBLN2, ITGA6, LRPAP1, Ly9, NT5E, PITPNC1, PLCG1, OBSCN, RHOH, SPTBN1, SPOCK2 and SPRY1." (PMID 41159936, 2025). "In the 18 cancer types from TCGA, we calculated tissues with mutations of ADAM12, MMP1, SERPINE1, PLOD3, and P4HA3, and they had limited mutations, and their mutation sites had few significant effects on gene expression or function gain across the 18 cancer types." (PMID 34121340, 2021). "Similarly, ADAM12 has been associated with invasion and we hypothesized that ADAM12L interacts with ZO-1 in invadopodia-like structures from cancer cells." (PMID 29765546, 2018).
cancer (continued). "Among the DEGs in the three above‐mentioned pathways, ADAM12 and CYP1B1 are overexpressed in the obese group compared to the other groups and were selected for further studies due to their relevance in cancer." (PMID 39806854, 2025). "The results indicated that the gene expression of ADAM12, FLRT2, and SLIT2 was higher in ER alpha-positive cancers." (PMID 39596804, 2024). "Recent mining of transcriptomic databases has identified MMP11 and ADAM metallopeptidase domain 12 (ADAM12) as potential CPAs, with MMP11 exhibiting high transcript levels in 25 different types of cancers." (PMID 38707901, 2024). "It is well-documented that both ADAM12 and BSG promote cancer progression, at least in part by regulating integrin and MMP activity." (PMID 38892056, 2024). "Given the proven significance of AS in cancer and the need for the identification of predictive biomarkers in CRC, we characterized the AS isoforms of MUC4 and ADAM12 in CRC." (PMID 36675796, 2023). "Together with ADAM12, the glycoprotein pentraxin-3 (PTX3) is also a critical protein promoting cell invasiveness of various cancers." (PMID 36009036, 2022). "Of the EMT pathway, the genes IL-6, SFRP4, FZD8, ADAM12, and CCN2 are known to promote cancer cell invasion and migration in multiple types of cancers." (PMID 35505422, 2022). "As a result, the higher protein expression levels of ADAM12, PLOD3, P4HA3, and SERPINE1 were detected in multiple types of cancer compared with the normal tissue specimens, which was consistent with their mRNA expression patterns." (PMID 34121340, 2021). "In general, the mRNA expression levels of ADAM12, MMP1, SERPINE1, PLOD3, and P4HA3 were correlated with immune infiltration score and macrophages and dendritic cells (DCs) in most types of cancer." (PMID 34121340, 2021). "Unsupervised principal component analysis with the main cancer invasiveness-enriched genes (ASPN, GLT8D2, OLFML2B, CRISPLD2, ADAM12, POSTN, and PRRX1) allowed for the discrimination of subgroups of BMAL1-dependent CRC patients (p = 9.9 × 10−4)." (PMID 34065633, 2021). "The most predominant ECM regulators, ADAM12, MMP1, SERPINE1, PLOD3, and P4HA3, have been classified as a five‐gene signature that produces a broad effect over 29 types of cancer." (PMID 34121340, 2021). "The ECM‐receptor interaction gene set was further analyzed for correlation with ADAM12, MMP1, SERPINE1, PLOD3, and P4HA3 in the 29 cancer types." (PMID 34121340, 2021). "In detail, both ADAM12 and MMP1 expression were upregulated in 16 cancer types (p < 0.05), PLOD3 was upregulated in 17 cancer types (p < 0.05)." (PMID 34121340, 2021). "MMP-9, MMP-14, ADAM-12 and ADAM-17 are some of the MPs that were found to have a significant role in several types of cancer." (PMID 32466129, 2020). "Several members of ADAMs, such as ADAM10, ADAM12, and ADAM15, have been reported to be overexpressed in human cancers." (PMID 32637415, 2020). "In our study, we analyzed serum levels of ADAM10, ADAM12, ADAM17, and ADAM28 in CRC patients, depending on clinical parameters to determine the potential role of adamalysines as a cancer biomarker." (PMID 31565100, 2019). "Whereas all of the assessed genes showed high expression in fibroblasts, several genes, including SPARC, ADAM12, TIMP2, MMP2, and COL5A2 were also expressed in carcinoma cells, albeit at lower levels." (PMID 27128408, 2016). "Here we explore the implication of ADAM12 in TGF-β-mediated epithelial to mesenchymal transition (EMT), a key process in cancer progression." (PMID 26407179, 2015). "ADAM12, VCAN and MET protein expression levels were also detected through western blot in cancer cells transfected with miR-144 mimics." (PMID 25927670, 2015). "The overexpression of ADAM8, ADAM9, ADAM10, ADAM12, ADAM15, ADAM17, and ADAM28 are reported from various cancers." (PMID 22272227, 2012).
cancer (continued). "In addition, ADAM12 cleaves various ECM molecules including gelatin, type IV collagen and fibronectin, suggesting a potential role of this enzyme in ECM digestion in cancer invasion and metastasis." (PMID 35565436, 2022). "Thus, ADAM12 functions as a shedder, adhesion molecule and ECM-degrading proteinase and is involved in cancer progression." (PMID 35565436, 2022). "Analysis of the various cancers revealed that several putative REST target genes, including Polo Like Kinase 1 (PLK1), ADAM Metallopeptidase Domain 12 (ADAM12), Troponin T1 (TNNT1), and cell migration-inducing and hyaluronan-binding protein (CEMIP, KIAA1199) were highly dysregulated." (PMID 35177031, 2022). "Finally, we identified two cancer stemness-related genes as potential hub biomarkers for COAD, including NRP2 and ADAM12." (PMID 34691191, 2021). "Among the non-haematological findings on ADAM12 are a table of expression of a disintegrin and metalloproteinases (ADAMs) in human cancers and their possible functions." (PMID 33507683, 2021). "Therefore, it is suggested that ADAM12 functions as a sheddase, adhesion molecule, and ECM-degrading proteinase, and is involved in cancer progression." (PMID 33507683, 2021). "Our microarray results suggest that MOB1 in NSCLC could predominantly regulate the expression of genes promoting cancer invasiveness such as MCAM and ADAM12." (PMID 32841529, 2020). "The other 6 putative CPAs demonstrated diverse expression profiles, ranging from those found only in a restricted set of cancer types (IGF2BP3, ADAM12), to those overexpressed in most cancer types but also demonstrating elevated expression in normal female reproductive tissues (CAPN6, MMP11)." (PMID 33087697, 2020). "However, the functional relevance of the correlation between ADAM12 and BSG in cancer remains elusive." (PMID 31013576, 2019). "Using cellular systems, an animal model, and bioinformatics, we find that a non-canonical but druggable TGF-β/KAT2A/TAK1 axis controls ADAM12 induction in normal and cancer cells." (PMID 30753595, 2019). "Next, we asked if our observation that KAT2A restricts ADAM12 expression, made in a non-transformed cell context, was also relevant in cancer." (PMID 30753595, 2019). "ADAMs shown to play a role in cancer include ADAM9, ADAM10, ADAM12, ADAM15 and ADAM17." (PMID 21906355, 2011). "Thus, not only ADAM12 and CYP1B1 can be seen as prognostic markers in RCC, but we also propose that interfering with the identified genes as well as hampering adiposity is an unmet adjuvant strategy in cancer therapy." (PMID 39806854, 2025). "Interestingly, most of the effects of knocking down ADAM12 and CYP1B1 were observed in overweight and obese‐derived adipocytes, confirming the relevance of these two genes not only in tumorigenesis but also in the crosstalk between adipose tissue and cancer." (PMID 39806854, 2025). "Interestingly, the absence of ADAM12 in T11 cancer cells sensitizes tumors to combination therapy targeting PD1/CTLA4 immune checkpoints." (PMID 38317965, 2024). "Interestingly, Several cancer studies have reported that ADAM12 was increased in breast cancer; however, little or no information is available for recurrent breast tissues from patients who underwent 5-FU adjuvant therapy." (PMID 28852196, 2017). "Moreover, the result from our group about the expressions of ADAM12, AREG, ER, JAGL1, PDGF-A, PN and SCG2 in whole CCA tissues (n = 20) showed that only AREG, PDGF-A and PN had higher level in cancer than those in benign liver tissues with statistical significance (data not shown)." (PMID 20096135, 2010).
infection (5 papers, 2006 to 2023). The state of being infected such as from the introduction of a foreign agent such as serum, vaccine, antigenic substance or organism. "Two ADAM12 genetic mutations (rs11244787 and rs1871054) led to an increased risk to transfer an infection with Trypanosoma cruzi, a parasitic euglenoids, from the mother to the newborn." (PMID 33392273, 2020). "ADAM10 and ADAM17 together with ADAM8 and ADAM9 seem to be the most relevant ADAM proteases in infection; however, some studies point toward an additional influence of ADAM12, ADAM15, and ADAM33." (PMID 33392273, 2020). "The ADAM12 mRNA induction was verified by RT-qPCR after an independent infection with the TAK1 expressing vector; in contrast a point mutant of TAK1 devoid of kinase activity (TAK1 catalytic dead, or TAK1 CD), failed to induce ADAM12 expression." (PMID 30753595, 2019).
adenocarcinoma (3 papers, 2006 to 2021). A common cancer characterized by the presence of malignant glandular cells. "However, in the adenocarcinoma subgroup, we showed an increase of ADAM-12 mRNA in the N0 stages when compared to N1 or N2 stages." (PMID 16495931, 2006).
gastrointestinal tumors (1 paper, 2022). "Previous work has demonstrated a distinctly stromal expression pattern of ADAM12 in gastrointestinal tumors." (PMID 35413826, 2022).
haematological diseases (1 paper, 2021). "Despite these findings, studies on ADAM12 in haematological disease are scarce when compared with non-haematological diseases, which makes the role of ADAM12 in CLL patients remains ambiguous." (PMID 33507683, 2021).
lung (1 paper, 2016). "Overexpression of CAR10 may also lead to up-regulation of ADAM12 to promote air pollution-induced lung carcinogenesis." (PMID 27322209, 2016).
ADAM12 also shares sentences with these, for which no sentence is quoted: brain cancer (3 papers); cervical cancer (3); lung adenocarcinoma (3); atherosclerosis (2); hypertrophic obstructive cardiomyopathy (2); neurodegenerative disease (2); stomach cancer (2); amyotrophic lateral sclerosis (1); autoimmune disease (1); cardiovascular disease (1); cecum adenocarcinoma (1); childhood asthma (1); chronic lymphocytic leukemia (1); chronic skin ulcers (1); connective tissue disorder (1); coronary artery disease (1); dyskeratosis congenita (1); esophageal adenocarcinoma (1); esophageal squamous cell carcinoma (1); esophagogastric adenocarcinoma (1); fibromatosis (1); fibrosis (1); giant cell tumor (1); ischemia (1); laryngeal squamous cell carcinoma (1); mesenchymal tumors (1); mucinous adenocarcinoma (1); multiple myeloma (1); nasal polyp (1); nasal septum deviation (1).
A further 18 diseases each share a sentence with ADAM12 in 1 paper.